SEPHS1 (selenophosphate synthetase 1)
Description:
Core component of the zincore complex, a heterotetramer that acts as a molecular 'grip' to stabilize transcription factors at DNA-binding sites across the genome, thereby controlling gene expression. The zincore complex binds specifically to zinc finger transcription factors, such as ZFP91, ZNF652, ZNF526 and PRDM15, and stabilizes them onto their cognate DNA motif. Within the complex, SEPHS1, recognizes and binds the backbone of zinc fingers of transcription factors in a sequence-independent manner via its arginine clamp, enhancing their DNA-binding stability. Plays an essential role in redox homeostasis. May also be involved in selenocysteine biosynthesis by catalyzing formation of selenophosphate from selenide and ATP. Its role in selenocysteine biosynthesis is however unclear and several studies suggest that it does not act as a selenophosphate synthase in vivo or plays an non-essential role. Required for cardiac differentiation (By similarity).
Synonyms: SELD; SPS; SPS1; VERBRAS2
Tractability: Small molecule: a structure with a bound ligand is known; it has a high-quality binding pocket. Antibody: UniProt places it where antibodies can reach, with high confidence; its Gene Ontology location is reachable by antibodies, with high confidence. PROTAC: ubiquitination databases record sites on it; its protein half-life has been measured.
Gene: Protein-coding gene on chromosome 10 (13,317,425 to 13,348,596, reverse strand). Ensembl gene ENSG00000086475.
Subcellular location: Nucleus; Chromosome; Cytoplasm; Cell membrane (Isoform 1); Nucleus membrane; Cytoplasm (Isoform 2); Cytoplasm (Isoform 3); Cytoplasm (Isoform 4)
Subcellular location (Human Protein Atlas): Nucleoplasm
Gene Ontology:
Molecular function: identical protein binding; protein binding; ATP binding; GTP binding; selenide, water dikinase activity
Biological process: cell redox homeostasis; selenocysteine biosynthetic process; protein modification process
Cellular component: chromosome; cytoplasm; nuclear membrane; nucleus; plasma membrane
Genetic constraint (gnomAD): Loss-of-function variants: 3 observed, 30.48 expected, observed/expected ratio (o/e) 0.0984, 90% interval 0.044 to 0.25. The upper end of that interval is the gene's LOEUF score, 0.25, which puts it in group 1 of 6, group 1 being the genes least tolerant of losing a copy. Missense variants: 236 observed, 483.21 expected, observed/expected ratio (o/e) 0.49, 90% interval 0.44 to 0.54. Synonymous variants: 183 observed, 185.2 expected, observed/expected ratio (o/e) 0.99, 90% interval 0.88 to 1.12.
Homologues: Orthologues: macaque SEPHS1 (100% identical), dog SEPHS1 (99% identical), guinea pig SEPHS1 (99% identical), mouse Sephs1 (99% identical), rat Sephs1 (99% identical), pig SEPHS1 (99% identical), rabbit SEPHS1 (97% identical), tropical clawed frog sephs1 (97% identical), zebrafish sephs1 (97% identical), chimpanzee SEPHS1 (87% identical), Drosophila melanogaster Sps1 (69% identical), Caenorhabditis elegans seld-1 (48% identical), and 1 more. Paralogues in human: SEPHS2 (75% identical).